DXO (decapping exoribonuclease)
Description:
Decapping enzyme for NAD-capped RNAs: specifically hydrolyzes the nicotinamide adenine dinucleotide (NAD) cap from a subset of RNAs by removing the entire NAD moiety from the 5'-end of an NAD-capped RNA. The NAD-cap is present at the 5'-end of some RNAs and snoRNAs. In contrast to the canonical 5'-end N7 methylguanosine (m7G) cap, the NAD cap promotes mRNA decay. Preferentially acts on NAD-capped transcripts in response to environmental stress. Also acts as a non-canonical decapping enzyme that removes the entire cap structure of m7G capped or incompletely capped RNAs and mediates their subsequent degradation (By similarity). Specifically degrades pre-mRNAs with a defective 5'-end m7G cap and is part of a pre-mRNA capping quality control (By similarity). Has decapping activity toward incomplete 5'-end m7G cap mRNAs such as unmethylated 5'-end-capped RNA (cap0), while it has no activity toward 2'-O-ribose methylated m7G cap (cap1). In contrast to canonical decapping enzymes DCP2 and NUDT16, which cleave the cap within the triphosphate linkage, the decapping activity releases the entire cap structure GpppN and a 5'-end monophosphate RNA (By similarity). Also has 5'-3' exoribonuclease activities: The 5'-end monophosphate RNA is then degraded by the 5'-3' exoribonuclease activity, enabling this enzyme to decap and degrade incompletely capped mRNAs. Also possesses RNA 5'-pyrophosphohydrolase activity by hydrolyzing the 5'-end triphosphate to release pyrophosphates (By similarity). Exhibits decapping activity towards FAD-capped RNAs. Exhibits decapping activity towards dpCoA-capped RNAs in vitro (By similarity).
Synonyms: DOM3L; DOM3Z; NG6
Tractability: Antibody: its Gene Ontology location is reachable by antibodies, with high confidence; the Human Protein Atlas places it where antibodies can reach.
Gene: Protein-coding gene on chromosome 6 (31,969,810 to 31,972,509, reverse strand). Ensembl gene ENSG00000204348.
Subcellular location: Nucleus
Subcellular location (Human Protein Atlas): Cytosol; Nucleoplasm; Plasma membrane
Pathways (Reactome):
Metabolism of RNA: Nuclear RNA decay
Gene Ontology:
Molecular function: protein binding; RNA NAD+-cap (NAD+-forming) hydrolase activity; 5'-3' exonuclease activity; magnesium ion binding; mRNA 5'-diphosphatase activity; mRNA binding
Biological process: mRNA catabolic process; NAD-cap decapping; nuclear mRNA surveillance; nucleic acid metabolic process; RNA destabilization
Cellular component: nucleoplasm; nucleus; cytosol
Genetic constraint (gnomAD): Loss-of-function variants: 42 observed, 42.97 expected, observed/expected ratio (o/e) 0.98, 90% interval 0.76 to 1.26. The upper end of that interval is the gene's LOEUF score, 1.26, which puts it in group 5 of 6, group 1 being the genes least tolerant of losing a copy. Missense variants: 495 observed, 540.73 expected, observed/expected ratio (o/e) 0.92, 90% interval 0.85 to 0.99. Synonymous variants: 193 observed, 211.1 expected, observed/expected ratio (o/e) 0.91, 90% interval 0.81 to 1.03.
Homologues: Orthologues: chimpanzee DOM3Z (99% identical), macaque DXO (98% identical), rabbit DXO (92% identical), guinea pig DXO (92% identical), dog DXO (91% identical), pig DXO (91% identical), rat Dxo (91% identical), mouse Dxo (90% identical), tropical clawed frog dxo (52% identical), zebrafish DXO (29% identical), Caenorhabditis elegans dom-3 (24% identical), Drosophila melanogaster Rai1 (24% identical), and 9 more.
Diseases named in the same sentence as DXO in open-access papers:
DXO is named in the same sentence as 14 diseases in open-access papers, as found by Europe PMC text mining. Sharing a sentence is not in itself a finding about the gene and the disease. The quoted sentences say what the papers report.
autoimmune disease (2 papers, 2024 to 2025). A disorder resulting from loss of function or tissue destruction of an organ or multiple organs, arising from humoral or cellular immune responses of the individual to their own tissue constituents. "Six genes in the MHC Class III region, DDX39B, DXO, LSM2, NELFE, PRRC2A, and SKIV2L, encode RBPs and have a well-defined role in post-transcriptional gene regulation and RNA monitoring, and these genes may have important functions in immunity and be associated with autoimmune diseases." (PMID 38770048, 2024).
asthma (1 paper, 2024). "For example, DXO (celiac disease-related gene) and PSMB9 (alopecia areata-related gene) could modulate CDSN (autoimmune hypothyroidism-, psoriasis-, asthma-, and Graves’ disease-related gene) expression." (PMID 39009607, 2024).
bladder cancer (1 paper, 2019). "We demonstrated that upregulation NPL4 binds directly to DXO and induces its degradation, whereas DXO regulates bladder cancer cell proliferation via destabilization of cyclin D1 mRNA." (PMID 31164795, 2019).
celiac disease (1 paper, 2024). An autoimmune genetic disorder with an unknown pattern of inheritance that primarily affects the digestive tract. "The proteomic analysis demonstrated that DXO (celiac disease- and T1D-related gene) and PSMB9 (alopecia areata-related gene) significantly altered the blood expression of CDSN, hinting that there might be a network of mutual regulatory mechanisms between these autoimmune-related genes." (PMID 39009607, 2024).
leukemia (1 paper, 2025). A malignant (clonal) hematologic disorder, involving hematopoietic stem cells and characterized by the presence of primitive or atypical myeloid or lymphoid cells in the bone marrow and the blood. "A half of these proteins have no reported relationship with leukemia, i.e., LTB4R2, DDX39B, ZNF668, ZNF788, and DXO." (PMID 40699783, 2025).
cancer (2 papers, 2020 to 2021). A tumor composed of atypical neoplastic, often pleomorphic cells that invade other tissues. "Few studies have investigated the biological role of DXO (Decapping and exoribonuclease protein) in cancers." (PMID 34831362, 2021).
infection (1 paper, 2024). The state of being infected such as from the introduction of a foreign agent such as serum, vaccine, antigenic substance or organism. "Next, we checked whether the depletionof the NAD cap on U1 RNA in HIV-1-infected cells is not caused bythe upregulation of DXO or Nudt12 upon infection; however, Westernblot and RT–qPCR analysis showed that the levels of DXO aresimilar in the control and HIV-1-infected cells." (PMID 38747804, 2024).
DXO also shares sentences with these, for which no sentence is quoted: autoimmune hypothyroidism (1 paper); Graves disease (1); HIV-1 infection (1); melanoma (1); psoriasis (1); systemic lupus erythematosus (1); tumor (1).